IL6 (interleukin 6)
Diseases named in the same sentence as IL6 in open-access papers (continued):
Sharing a sentence is not in itself a finding about the gene and the disease.
cancer (continued). "IL-6/STAT3 upregulates the expression levels of MMPs including MMP-1, MMP-2, MMP-7, MMP-9 via directly interacting with their promotors in several aggressive cancers." (PMID 38245798, 2024). "We and others have shown, both in MPM and in other cancers, that modulation of the number and activity of chemoresistant ALDHbright cells in CRC may be mediated by IL-6-stimulated STAT3." (PMID 38791392, 2024). "IL-6 facilitates replicative immortality in cancer cells by influencing the equilibrium between cancer stem cells and non-stem cells through regulation of OCT-4 gene expression." (PMID 38689325, 2024). "Inflammatory cytokines like IL-6 not only contribute to the generation of CSCs, but also play a role in regulating the equilibrium between CSCs and non-stem cell cancer cells." (PMID 39184916, 2024). "Important hallmarks of cancer terms include KRAS signaling up and IL-6/JAK/STAT3 signaling." (PMID 38627442, 2024). "Additionally, TNF-α potentiates the activity of IL-6, which activates STAT3 expression in cancer cells, enhancing the self-renewal and invasive capabilities of pancreatic cancer stem cells." (PMID 39680287, 2024). "However, chronic infection with Helicobacter pylori can lead to a shift towards M2 polarization, driven by continuous IL-6 production, highlighting the dynamic nature of TAM polarization and its impact on cancer progression." (PMID 39286635, 2024). "Altogether, previous studies and the present findings indicate that IL-6 may play a role in long-term CRCI and particularly on episodic memory impairment after cancer treatment, and that it might be used as a predictive marker." (PMID 38840166, 2024). "Cancer patients treated with DOXO experienced high levels of CRP, erythrocyte sedimentation rate, IL-6, and IL-1β that may contribute to additional complications, including organ dysfunction or failure." (PMID 38818214, 2024). "Siltuximab, a monoclonal antibody binding to and inhibiting the function of IL-6, as a single drug, did not achieve cancer control as shown in multiple studies on various solid tumors." (PMID 39518029, 2024). "Pre-treatment circulating levels of serum IL-6, HGF, and CCR may serve as independent predictive and prognostic biomarkers in advanced cancer patients treated with ICIs-based systemic therapy." (PMID 38776028, 2024). "Targeting the interleukin-6 (IL-6)/glycoprotein 130 (GP130) signaling pathway holds significant promise for cancer therapy given its essential role in the survival and progression of various cancer types." (PMID 39451730, 2024). "In cancer tissue, there were significant correlations between Cr level with expression of Bax, AKT, and P38 while Cd level was significantly correlate with Bax, IL-6, AKT, and P38expression." (PMID 38072891, 2024). "IL-6 transduction signaling mechanisms activate various pathological pathways, such as JAK/STAT3, Ras/MAPK, and PI3K-PKB/Akt, and regulate CD4+T cell and VEGF levels, leading to cancer, inflammatory diseases, and neurological diseases." (PMID 38645489, 2024). "IL-11 exhibits significant thrombopoietic capacity, and unlike IL-6, which promotes the proliferation of a variety of cancer cells, the U.S. FDA has approved the clinical use of rhIL-11." (PMID 38256942, 2024). "Our results showed that IL-6, IL-12, TNF-α, and NF-κB increased significantly in the AOM group for both normal diet and HFD but decreased significantly when treated with PB showing that PB has anti-inflammatory effects in cancer cells." (PMID 39845239, 2024). "Beyond IL-6, other members of the IL-6 cytokine family, such as IL-11, leukemia inhibitory factor (LIF), and oncostatin M (OSM), also play critical roles in the interplay between inflammation and cancer." (PMID 39421736, 2024).
cancer (continued). "Previous studies pointed to an up-regulatory effect of M2 TAMs and TAFs on the expression of IL-10 and TGF-β, IL-6 and MMPs, and the endothelial mesenchymal transition (EMT)-related genes, e.g., vimentin in cancer cells which subsequently dampened the efficacy of ICD." (PMID 37612575, 2024). "The pro-inflammatory state induced by chronic HPV infection, characterized by the upregulation of cytokines such as interleukin-6 (IL-6) and tumor necrosis factor-alpha (TNF-α), further promotes oncogenesis by creating a microenvironment conducive to cancer development." (PMID 39338421, 2024). "The link between MMP9 and inflammation is evident from its correlation with inflammatory mediators like IL-6 and CRP, indicating an inflammatory environment that may boost MMP9 levels, thereby facilitating cancer’s advancement." (PMID 39664453, 2024). "Given the significant role of IL-6 in the constitutive activation of STAT3, some therapeutic approaches to downregulate the IL-6 signaling pathway have become targets for the therapies of various types of cancer." (PMID 38256080, 2024). "In conclusion, pre-treatment circulating levels of serum IL-6, HGF, and CCR may serve as independent predictive and prognostic biomarkers in advanced cancer patients treated with ICIs-based systemic therapy." (PMID 38776028, 2024). "More aggressive cancer cells grew more quickly when the cytokines TNF-α and IL-6 were present." (PMID 38506948, 2024). "In addition, administration of EPA to a cancer patient resulted in decreased production of cytokines that promote inflammatory responses (TNF-α, IL-1, and IL-6)." (PMID 39597805, 2024). "Our results showed that IL-6 was significantly expressed at higher levels in cancer tissues of BC than in non-cancerous tissues." (PMID 38072891, 2024). "IL6 is known to stimulate aerobic glycolysis and HIF-1α in cancer cells." (PMID 38650935, 2024). "Bcl-2, Bax, IL-6, AKT, and P38 play a role in cancer progression." (PMID 38072891, 2024). "While therapies targeting IL-1 and IL-6 have shown promise in patients with cachectic cancer, they have not consistently demonstrated a significant impact on SMM." (PMID 39456555, 2024). "In this study, we identified CAFs, rather than cancer cells, are the predominant source for secreting IL-6 in the local niche." (PMID 38459511, 2024). "Also, the innate immune cells present in the TME secrete cytokines, including IL-6, TNF-α, and IL-1, which, through recruiting more of the inflammatory cells, further potentiate this effect, contribute to cancer cell proliferation and survival." (PMID 39201656, 2024). "Also, cGAS-dependent IL-6 secretion and IL6R signaling have recently been demonstrated to provide pro-survival signals in cancer cells, including TNBCs59." (PMID 38167507, 2024). "By targeting IL-6 signaling, PTS may suppress inflammation-driven tumorigenesis and inhibit cancer cell proliferation and survival." (PMID 38756274, 2024). "The use of CIS in cancer therapy is usually accompanied by inflammation and increased pro-inflammatory cytokines like tumor necrosis factor-alpha (TNF-α), inducible nitric oxide synthase (iNOS), interleukin-1 beta (IL-1β), and Interleukin-6 (IL-6)." (PMID 39765772, 2024). "In this study, we demonstrated the interaction between two important proinflammatory cytokines (CCL5 and IL-6) and cancer cells; however, no change in IL-6 expression was observed in RNA extracted from whole tumors." (PMID 39126553, 2024). "Moreover, the clinical development of monoclonal antibodies and receptor inhibitors targeting protumor cytokines such as VEGF, IL-6, and TGF-β represents another milestone in cancer therapy." (PMID 39034318, 2024). "The phosphorylated TBK1 and IKK stimulate the transcription factors interferon nuclear factor κB (NF-κB) and interferon regulatory factor 3 (IRF3), eliciting the expression of proinflammatory cytokines such as interleukin 6 (IL-6) and type I interferons (IFN-I) to kill cancer cells." (PMID 38999073, 2024).
cancer (continued). "Moreover, the adipocyte-derived interleukin-6 (IL-6) and leptin regulate epithelial-mesenchymal transition (EMT) in cancer cells and supports stem cell renewal and chemoresistance 43-47." (PMID 38370376, 2024). "Moreover, the E3 ubiquitin ligase NEDD4L interacts with GP130, promoting its ubiquitination in tumors and thwarting the activation of the IL-6/GP130/STAT3 signaling axis, thereby exhibiting anti-cancer properties." (PMID 38828409, 2024). "Accordingly, the inhibition of inflammation promoting cancer is anticipated by targeting key mediators and/or regulatory factors (such as NF‐κB and STAT3) of inflammatory pathways and cytokines (e.g., IL‐1, TNF, and IL‐6)." (PMID 38766879, 2024). "Also, IL-6 has been related to TMX resistance through a decrease in ER-α levels; however, the cancer cells continue expressing genes under E2 regulation, suggesting the participation of another receptor for this hormone." (PMID 39201674, 2024). "The hallmarks of cancer-fibroblast interactions, consisting of caveolin 1 (Cav1) and mono-carboxylate transporter 4 (MCT4) (metabolic coupling markers), along with IL-6, TGFβ, and lactate secretion, are considered robust biomarkers predicting recurrence and metastasis." (PMID 38361760, 2024). "IL6 can rapidly convert the non-stem cancer cell population to CSCs, as evident in various cancers such as breast, prostate, and bladder cancers." (PMID 39766086, 2024). "Taken IL-6 and VEGF as examples, inhibition of IL-6 or its receptors may downregulate VEGF production from cancer cells and inflammatory cells because IL-6 is known to instigate VEGF production." (PMID 38482486, 2024). "Both TGF‐β and IL‐6 can activate signalling pathways in EMT and drive cancer progression." (PMID 38362620, 2024). "Likewise, TAMs conditioned by CRC notably elevate IL-6 secretion, activating the Jak2/STAT3 pathway and indirectly boosting forkhead box Q1 (FoxQ1) expression in cancer, thus reinforcing EMT and cancer stem cell attributes." (PMID 39286635, 2024). "The results indicate that varying solanine concentrations (10, 20, and 30 μM) considerably reduce the expression of iNOS, IL-6, cyclin-D1, and PCNA proteins in KB-ChR-8-5 cells, suggesting that solanine has the ability to significantly decrease the formation of malignant tumors." (PMID 39124760, 2024). "Unfortunately, as demonstrated in the therapeutic application of TCZ and other anti-IL-6 signaling drugs, their anti-cancer effect was not prominent." (PMID 38715108, 2024). "Moreover, S-Nitrosylation of STAT3 at Cys259 disrupts the IL-6 induced STAT3 phosphorylation for genes required for inflammatory/immune responses and cell proliferation, including cancer." (PMID 38245798, 2024). "Solute factors secreted by CAFs, such as IL-6, IL-33, TGF-β, CAF-derived cardiotrophin-like cytokine factor 1 (CLCF1), and stromal cell derived factor-1 (SDF-1), can produce cancer-promoting signals and participate in the signal transduction of cancer cells and other cells within the TME." (PMID 39595654, 2024). "The IL-6/GP130 signaling pathway is increasingly being recognized as a key driver in the development, survival, and drug resistance of various cancers, making it a promising target for cancer therapy." (PMID 39451730, 2024). "IL-6 activates the Janus tyrosine kinase/signal transducer and activator of the transcription 3 (JAK/STAT3) pathway, and STAT3 modifies the transcription of several genes promoting cancer." (PMID 38541242, 2024). "The available clinical data across cancer types suggests that IL-6 inhibition as monotherapy is unlikely to provide meaningful oncologic benefit." (PMID 38689325, 2024). "NK cells with reduced anti-cancer functions in the immunosuppressive lung tumor microenvironment acquire pro-cancer properties and begin to produce and secrete VEGF and CXCR2 ligands such as CXCL1, CXCL2, and CXCL8/IL-8 as well as IL-6, CCL2, matrix metalloproteinases (MMP), and many others." (PMID 38673949, 2024).
cancer (continued). "If we can therapeutically reset the cytokine balance, (specifically, IL-6), then we could suppress inflammation, the SASP, and with it, control cancer." (PMID 39512605, 2024). "Human-derived cytokines interleukin-2 (IL-2), IL-4, IL-6, IL-12, IL-10, tumor necrosis factor α (TNF-α), and interferon-γ (IFN-γ) could be detected in all cancer cell–bearing mice by cytokine level measurement." (PMID 39606226, 2024). "Besides, small-molecule inhibitors targeting downstream elements of the IL-6 signaling pathway, such as JAK and STAT3, show promise in cancer treatment as well." (PMID 39034318, 2024). "In cancer models, TNF-α, IL-6, and IL-8 strongly induce cell migration and in vivo metastasis." (PMID 38612423, 2024). "The administration of a drug combination using 5-fluorouracil, doxorubicin, and cyclophosphamide triggers an IL-6-dependent NF-κB signaling cascade, which promotes stemness to non-stem cancer cells and consequently induces MDR in BC." (PMID 37789138, 2024). "Additionally, just like CAFs, H-shNC exo-treated NFs released more pro-inflammatory cytokines, including IL-6, IL-8, and TGF-β, which act as key players in remodeling the TMe and promoting carcinoma development." (PMID 38485986, 2024). "IL‐6, which is produced by THP‐1 cells, may be key in inducing tMEK/Erk activation in radioresistant cancer cells." (PMID 37347290, 2023). "Furthermore, Fc-VFD inhibits the secretion of VEGF-A, IL-6, TGF-β, or IL-10 from endothelial, cancer cells, and M2 macrophage, which reprograms immunosuppressive TME." (PMID 35895109, 2023). "While the cancer presence alone did not elicit gene expression changes in these adipose tissues, there was a significant increase in Ccl4 (in pmWAT only), Ccl2 and Il6 in both WATs in the HFD/MOSETICv group." (PMID 38264656, 2023). "Upon IL-22 and IL-6 stimulation in epithelial cells, the activation of the STAT3 pathway not only enhances cell viability but also suppresses suppressing apoptosis, underscoring its significance in the transition from IBD to cancer." (PMID 38288125, 2023). "In addition, elevated IL-6 levels hyperactivate the JAK/STAT3 signaling pathway, as has been observed in many cases of hematopoietic or solid malignancies." (PMID 37240202, 2023). "Additionally, the blockade of IL-6 activated CD8+ T-cell accumulation and led to elevated PD-L1 expression in cancers, suggesting possible sensitization to anti-PD-1 therapy." (PMID 36823670, 2023). "Here, we have found the prominent expression of il-6, il-10 and il-1β receptors on respective cancer cells, without any noticeable change in the expression of vegf receptor." (PMID 38304256, 2023). "A non-inflammatory senescence-associated secretory profile was induced, significantly decreasing inflammatory cytokines and chemokines such as IL-6, IL-8, TNF, RANTES, and MCP-1; this is consistent with the lower incidence of thyroid inflammation and cancer in men." (PMID 37190127, 2023). "Moreover, according to the same research, IL-6 induces cancer cachexia through regulation of WAT lipolysis in early-stage and browning of WAT in late-stage cancer cachexia." (PMID 37760840, 2023). "The immune pathway mediated by pro-inflammatory cytokines such as IL-6 and TNF-α interferes with the biological effects of the insulin receptor downstream signaling and results in IR, which is also found to be closely involved in cancer development." (PMID 36969019, 2023). "Therefore, we focused on upregulated secretome genes that included several known cachexia mediators described in pan-cancer and NSCLC, such as IL6, IFNG, LIF, CCL2, and CSF3." (PMID 36774484, 2023). "Furthermore, we previously found that certain cytokines and transcriptional factors, including IL-6, IL10, IL-27, STAT, and NF-kB, regulate PD-L1 expression in various cancers." (PMID 36757936, 2023).
cancer (continued). "Hence, the correlation between TMMV and established predictive biomarkers of cancer cachexia, including IL-1, TNF-alpha, IL-6, CRP, and serum albumin, warrants investigation." (PMID 37959329, 2023). "The current study identified VEGF-A, TNF-α, CCL2, IL-6, and IFN-γ (CCL2, IL-6, and IFN-γ after Bonferroni correction) as additional plasma biomarkers reflecting cancer presence, in addition to anti-TIF1-γ antibody, among anti-TIF1-γ antibody-positive DM patients." (PMID 36357631, 2023). "Further analysis by treatment revealed that both Il6 and Csf3 gene expression increased in Fibro/CAFs 1 after chemotherapy, while there was a marginal decrease in expression of Il6 in cancer cells (D2.0R 2) with no Csf3 expression." (PMID 37699010, 2023). "In addition, IL-6 has been identified as a regulator of epithelial–mesenchymal transition (EMT) in normal breast cells, resulting in cancer cells with stem-like characteristics." (PMID 36900322, 2023). "Cytokines, such as interleukin 6 (IL-6), interferon alpha (IFNα), transforming growth factor-β (TGF-β), and others, have been investigated as potential biomarkers for predicting ICIs treatment response in various cancers, including HCC." (PMID 38187399, 2023). "Melanoma CSCs can educate neutrophils to support cancer progression in several ways, such as neutrophil recruitment via TGF-β, IL6, and IL8, enhancing N2-polarization by the activation of ERK, STAT3, and P38 pathways, as well as the overexpression of CXCR2 and NF-kB." (PMID 36672697, 2023). "Daily consumption of dark tea can achieve cancer prevention by inhibiting pro-inflammatory cytokines TNF-α, IL-1β, and IL-6 and increasing anti-inflammatory cytokines IL-10 and IL-22, which is mainly attributed to the down-regulation of the NF-κB signaling pathway." (PMID 37764687, 2023). "Cancer stage modified the association between randomized group and hs-CRP (Pinteraction=0.022) and IL6 (Pinteraction<0.001) but not sTNFαR2 (Pinteraction=0.39)." (PMID 38148846, 2023). "Furthermore, taxanes, including paclitaxel, induced an increase in IL-1β, IL-6, and TNF-α levels in patients with cancer." (PMID 37275575, 2023). "A time course study with IL-10-neutralized MDSCs supernatant on Dox resistant cancer cells, showed downregulated p-STAT3 expression as early as 60 mins post treatment, whereas, IL-6- neutralized supernatant has showed decreased p-STAT1 activation after 240 mins of treatment." (PMID 38304256, 2023). "In parallel, we also focus on cytokine IL-6, a critically important master regulator of the interplay between cancer cells and non-malignant cells within the cancer ecosystem." (PMID 36835029, 2023). "Antibody targeting of protumor cytokines (IL-6, G-CSF) or inhibition of cytokine signaling via MEK/ERK pathway using selumetinib prior to docetaxel treatment prevented cancer dormancy outgrowth suggesting a novel therapeutic strategy to prevent cancer recurrence." (PMID 37699010, 2023). "Interestingly, plasma VEGF-A, TNF-α, CCL2, IL-6, and IFN-γ cytokines levels were significantly enhanced in the Untreated Cancer TIF1-γ-DM group than in the Non-cancer TIF1-γ-DM group." (PMID 36357631, 2023). "For example, fibroblasts could secrete TGF-β2, which can promote levels of CXCL12, IL-6 and VEGF-A, inducing immune evasion of cancer cells and angiogenesis." (PMID 36698173, 2023). "IL-6 is upregulated in excessive inflammatory conditions in CB2−/− males and has been shown to direct hematopoiesis towards a myeloid output where such abnormal myelopoiesis contributes to the upregulation of MDSCs in cancer and inflammation." (PMID 36835468, 2023). "In addition, gene network analysis regarding to mass-type ER-positive cancers showed that ESR1, BIRC5, CAV1, FGFR1, IL6, MIR27, and PTTG1 were upregulated." (PMID 37391754, 2023).